TLR2 (toll like receptor 2)
Diseases named in the same sentence as TLR2 in open-access papers (continued):
Sharing a sentence is not in itself a finding about the gene and the disease.
breast carcinoma (65 papers, 2010 to 2026). "Among these, are amplifications of the gene coding for IRAK1, which is found in 23.8% of breast cancers, and mutations producing constitutively active forms of TLR2." (PMID 33321934, 2020). "TLR2 signaling has been demonstrated to induce migration in human breast cancer cells) and ligation of TLR7 and -8 has been associated with proliferation and chemoresistance in pancreatic cancer (TLR7 and -8)." (PMID 27941651, 2016). "Our study illustrated a new TLR2-mediated pathway which disclosed the effects of bacterial component on breast cancer cell independent on infection-associated inflammation." (PMID 20520770, 2010). "Our study reveals a direct relationship of cancer cells with pathogenic bacteria, suggesting a TLR2-mediated mechanism in bacterial infection-associated human breast cancer metastasis." (PMID 20520770, 2010). "Indeed, data from the Kaplan–Meier plotter (kmplot.com (accessed on 21 December 2023)) and from the literature indicate that high expression of TLR2 is associated with poor relapse-free survival in breast cancer patients." (PMID 38203626, 2023). "Furthermore, high TLR2 mRNA levels are associated with poor relapse-free and overall survival in breast cancer patients who underwent surgery, as well as in patients treated with endocrine therapy or chemotherapy." (PMID 38203626, 2023). "Circulating levels of TLR2 are associated with an increased risk of breast cancer." (PMID 35805158, 2022). "Indeed, high TLR2 expression is associated with poor response to chemotherapy in pancreatic and breast cancer patients, suggesting that it could represent a good target to improve chemotherapy efficacy in OSA patients as well." (PMID 41375047, 2025). "Notably, polymorphisms in the TLR2 gene, such as rs5743708, may predispose individuals to breast cancer." (PMID 38903515, 2024). "Concurrently, macrophages treated with breast cancer-derived exosomes caused significant increases in NF-κβ activation and production of inflammatory cytokines (including IL-6 and TNFα) compared to exosomes from normal breast cells through exosomal binding to the Toll-like receptor 2 (TLR2)." (PMID 26601108, 2015). "CLEC2D has been reported to form heterodimers with TLR2, and we previously demonstrated a correlation between TLR2 immunoreactivity and increased proliferation and shorter disease-free survival in breast cancer." (PMID 40938562, 2026). "Genetic deletion of TLR2 in macrophages found to abolish NF-κB activation triggered by breast cancer secreated exosomes." (PMID 40443670, 2025). "The binding of extracellular HMGB1 to TLR2/4 activates MyD88‐dependent NF‐κB/STAT3 signaling in breast cancer cells, driving epithelial‒mesenchymal transition and chemoresistance, while simultaneously polarizing TAMs toward the M2 phenotype." (PMID 40727252, 2025). "A recent study proposed a model in which breast cancer-exosomes activate TLR2-mediated NF-κB signaling in human macrophages, leading to cytokine production, supporting and aligning with these findings." (PMID 40443670, 2025). "Conversely, our group demonstrated that the tumor-targeted inhibition of TLR2 represents a key strategy in malignancy such as breast cancer, where high TLR2 expression correlates with poor prognosis and chemoresistance." (PMID 41375047, 2025). "In breast cancer mouse models, combined TLR2/STING agonist therapy significantly inhibits tumor growth and induces systemic antitumor immunity." (PMID 40567603, 2025). "Clinical studies indicate a significant correlation between high TLR2 expression and poor prognosis in breast cancer patients." (PMID 41488647, 2025). "characterized TLR2WT and TLR2KO autochthonous mammary cancer mouse models, uncovering a pro-tumorigenic role of TLR2 in driving breast cancer progression and fostering resistance to chemotherapy." (PMID 38903515, 2024).
breast carcinoma (continued). "In breast cancer, TLR2 has been observed to both promote and inhibit tumor growth, highlighting its dual functionality and pleiotropic roles in tumorigenesis." (PMID 38903515, 2024). "For instance, analyses of human breast cancer samples consistently reveal elevated TLR2 expression, which correlates with poor overall survival and resistance to endocrine therapy in the luminal B subtype of breast cancer." (PMID 38903515, 2024). "TLR2 neutralizing antibodies also block the growth of two independent ERneg breast cancer xenografts in vivo." (PMID 38347830, 2024). "Conversely, TLR2 has recently emerged as a pivotal player in inhibiting tumor growth in breast cancer." (PMID 38903515, 2024). "Multiple studies have highlighted the adverse impact of TLR2 expression and activation on breast cancer outcomes." (PMID 38903515, 2024). "In the context of breast cancer, TLR2 and STING emerge prominently among PRRs for their potential in pioneering new therapeutic approaches." (PMID 38203626, 2023). "The conflicting reports on TLR2’s antitumor and protumor properties underscore the critical need to comprehend its context-dependent role in breast cancer for potential therapeutic advancements." (PMID 38203626, 2023). "Activation of TLR2 in mammary epithelial stem cells and in breast cancer cells enhances the expression of stemness-related genes, promoting the acquisition of CSC properties that contribute to treatment resistance and tumor recurrence." (PMID 38203626, 2023). "TLR2 mRNA expression is significantly higher in breast cancer than in normal tissues, with a higher expression in the triple-negative and HER2+ subtypes as compared to the luminal A and luminal B." (PMID 38203626, 2023). "The chemoresistance ability of TLR2 is expressed with a low relapse-time in anticancer chemotherapeutic-treated breast cancer patients and with a decrease in the sensitivity of several breast cancer cell lines to doxorubicin." (PMID 37822929, 2023). "Wenjie Xie and colleagues have demonstrated that TLR2 activation promotes breast cancer cell survival, proliferation and invasion through the activation of NF-κB and the secretion of protumoral cytokines." (PMID 38203626, 2023). "This behavior is in line with another observation that showed an increase in the expression of TLR2 in breast cancer lines endowed with high metastatic ability." (PMID 37822929, 2023). "More recently, we demonstrated that TLR2 promotes breast cancer progression and metastasis in HER2+ transgenic mice in a cancer cell-intrinsic way." (PMID 38203626, 2023). "Collectively, this evidence strongly suggests that in breast cancer, the presence of TLR2 along with its endogenous or exogenous ligands can significantly influence a worse prognosis." (PMID 38203626, 2023). "We have previously demonstrated the upregulation of TLR2 in breast CSC-enriched tumorspheres compared to epithelial-like breast cancer cells." (PMID 38203626, 2023). "In breast cancer cells, TLR2 is overexpressed and can be activated by endogenous ligands such as HSPs, HMGB1 and other DAMPs, or by exogenous ligands derived from pathogens, like bacterial lipoproteins." (PMID 38203626, 2023). "The emerging conflicting roles of TLR2 and STING in breast cancer progression, associated with their therapeutic potential, have prompted us to focus on the role of these two PRRs in breast cancer." (PMID 38203626, 2023). "TLR2 activation in breast cancer cells upregulates the expression of vascular endothelial growth factor (VEGF) and other pro-angiogenic factors, fostering the formation of new blood vessels that support tumor growth." (PMID 38203626, 2023). "TLR2 is expressed by breast cancer cells and promotes CSC self-renewal, invasiveness and drug resistance." (PMID 38203626, 2023). "ARHGDIB and STAT1 are increased in models of breast cancer CTCs while STAB1 and TLR2 are increased in tumor-associated inflammatory cells in breast and colorectal cancer." (PMID 36176417, 2022).
breast carcinoma (continued). "An in vitro 4T1 mammary carcinoma cell model was used to verify TLR2 as a ubiquitous receptor that piloted phagocytosis of ferroptotic cells." (PMID 33432112, 2021). "In HER2+ breast cancer preclinical models, activation of Toll-like receptor 2 has been shown to augment trastuzumab-mediated cytotoxicity against HER2+ breast cancer cells." (PMID 32195333, 2020). "We are currently studying the combination of TLR2 targeting, chemotherapy, and immunotherapy in breast cancer preclinical models." (PMID 33321934, 2020). "In many cancer studies, such as gastric cancer, colorectal cancer, breast cancer, cervical cancer, Toll-like receptor (TLR)-2 (TLR2) has been determined as a pathogenic factor involved in tumorigenesis." (PMID 31710083, 2019). "TLR2 was highly expressed by two-fold in mammary cancer stem cells and inhibition of TLR2 signaling impaired in vitro mammosphere generation in MDA-MB-231 cells." (PMID 30728901, 2019). "TLR2 agonists fed to neu transgenic mice significantly inhibits breast cancer growth and leads to inhibition of immune responses by production of IL-10 and regulatory T-cells." (PMID 30517191, 2018). "Supporting our findings, it has recently been demonstrated that TLR-2 activation is also operative in human gastric and breast cancer." (PMID 28314957, 2017). "Stimulation of TLR2/4 in vitro induced expression of pro-inflammatory genes and a gene expression analysis of primary breast cancers showed a strong correlation between TLR4 expression and expression of pro-inflammatory mediators." (PMID 26392082, 2015). "For example, a recent study shows that systemic administration of breast cancer exosomes to mice results in inflammatory cytokine production by lung macrophages through the transmission of TLR2-activating molecules." (PMID 26177198, 2015). "In summary, invasion into matrigel invasion chambers by MDA-MB-231 breast cancer cells was increased when the TLR2/4 ligand LPS was added to the invading cells." (PMID 26392082, 2015). "When polysaccharide krestin (PSK), a TLR2 agonist was orally consumed in neu-transgenic mice, it significantly inhibited breast cancer growth by its action on the CD8 (+) T-cell and NK cells but not CD4 (+) T-cells." (PMID 24904578, 2014). "As an example of the application of this methodology, consider the case in which we want to evaluate the presence of TLR2 on the surface of breast cancer cell and the effect that it has on the AKT/PI3K network." (PMID 23734974, 2013). "Inherent defects in specifically the breast cancer CIC population PPRs TLR2 and TLR9 are likely to contribute to dysfunction in the initiation of the type I IFN response leading to a failure of feed-forward signal amplification via IRFs and STAT signaling." (PMID 21079774, 2010). "Not only TLR9 and TLR2, but also other TLRs are involved in the process of breast cancer development." (PMID 20618976, 2010). "In present study, we found that breast cancer cells of different metastatic abilities expressed differential levels of TLR2 positively relating to cellular invasiveness and adhesiveness." (PMID 20520770, 2010). "Our study shows that compared with nearly undetectable TLR2 level in untransformed breast cells, classic highly metastatic breast cancer MDA-MB-231 cells express high level of TLR2." (PMID 20520770, 2010). "Collectively, we illustrated a TLR2-mediated mechanism in metastatic breast cancer cell challenged by PGN, a major surface component of Gram-positive bacteria." (PMID 20520770, 2010). "We identified that highly metastatic breast cancer MDA-MB-231 cells expressed high level of Toll-like receptor 2 (TLR2) in contrast to poorly metastatic breast cancer cells and homogenous untransformed breast cells." (PMID 20520770, 2010). "The peptidoglycan of Staphylococcus aureus (PGN-SA) triggered breast cancer cell TLR2 with NF-κB, STAT3 and Smad3 activation contributing to the cancer cell invasiveness and adhesiveness." (PMID 20520770, 2010).
breast carcinoma (continued). "From these studies, we know that TLR9 and TLR2 play a key role in breast cancer proliferation and metastasis." (PMID 20618976, 2010). "We further report that PGN-SA elicited an augment of constitutive NF-κB activity via activation of TLR2 in breast cancer cells whereas TLR2 blockade or NF-κB activity inhibition decreased these cytokine secretions." (PMID 20520770, 2010). "The results above indicated that TLR2 activation by bacterial PAMPs of PGN promoted breast cancer cell invasiveness and adhesiveness as well as TLR2-NF-κB signalling activation." (PMID 20520770, 2010). "Taken together, high level TLR2 expressed in metastatic human breast cancer cells and mediated a bacterial component, PGN, to stimulate NF-κB activity resulting in STAT3 and Smad3 sequential activation, which contributed to invasiveness and adhesiveness." (PMID 20520770, 2010). "On the contrary, anti-TLR2 neutralizing antibody notably attenuated the number of invasive breast cancer cells." (PMID 20520770, 2010). "Propranolol, a β-adrenergic signaling antagonist, demonstrates palliative effects on breast cancer progression and survival, primarily through TLR2-directed immunomodulation, such as altering the polarization of macrophages, and increasing the activation of cytotoxic T cells and NK cells." (PMID 38903515, 2024). "Numerous pieces of evidence underscore the pivotal role of TLR2 in breast cancer." (PMID 38903515, 2024). "The capacity of TLR2 to thwart oncogenic AKT/mTOR signaling suggests that TLR2 agonists could be explored as potential breast cancer therapeutics, leveraging the innate immune response against tumors." (PMID 38903515, 2024). "In addition, the TLR2/MyD88 signaling pathway can activate the NF-κB and Wnt signaling pathways, ultimately inducing the proliferation of colorectal and breast cancer cells." (PMID 38785969, 2024). "explored the impact of exercise on monocyte function in breast cancer survivors, revealing that acute aerobic exercise downregulates TLR2 and TLR4 expression on monocytes and attenuates intracellular pro-inflammatory cytokine production, although the precise molecular mechanisms remain elusive." (PMID 38903515, 2024). "Moreover, a significant correlation was observed between high TLR2 expression and poor prognosis in breast cancer patients." (PMID 38203626, 2023). "Moreover, dysregulation of TLR2 has been reported as a prognostic biomarker in breast cancer by implying a dual role in carcinogenesis and chemoresistance." (PMID 37822929, 2023). "Indeed, F. nucleatum is detected in colon and breast cancer tissues, directly promoting tumor progression by activating TLR2 signaling in cancer cells and inducing immunosuppression, as described in the following paragraph." (PMID 38203626, 2023). "DAMPs such as HMGB1 and serum amyloid A 1 protein, secreted by breast cancer cells and elevated in the plasma and tumor biopsies from patients with advanced triple-negative breast tumors, induce an immunosuppressive response in neutrophils via TLR2." (PMID 38203626, 2023). "Importantly, TLR2 expression levels can predict the response to endocrine therapy with high accuracy in both luminal A and luminal B breast cancer patients." (PMID 38203626, 2023). "Furthermore, TLR2 is highly expressed in breast cancer stem cells, and TLR2 inhibition significantly attenuated the lung metastasis in animal models." (PMID 37153547, 2023). "Similarly, TLR2 deletion impairs tumorigenesis in MMTV–Wnt1 transgenic mice that spontaneously develop ERneg mammary tumors." (PMID 38203626, 2023). "As for TLR2, it has been reported to promote tumor growth in breast cancer and colon cancer." (PMID 35328684, 2022). "It was reported that genetic ablation of TLR2 in macrophages could abolish the NF-κB activation effect stimulated by breast cancer-derived exosomes." (PMID 34659412, 2021).
breast carcinoma (continued). "The relevance of the TLR2 signaling pathway in breast cancer is demonstrated by the fact that TLR2 expression has been found in human breast cancer samples, and that its expression is associated with poor overall survival and to resistance to endocrine therapy." (PMID 33321934, 2020). "Moreover, multiple genetic alterations that lead to increased TLR2 signaling have been identified in human breast cancer specimens." (PMID 33321934, 2020). "In pancreatic cancer and breast cancer, TLR2 promotes the proliferation of tumor cells." (PMID 32256204, 2020). "Additionally, TLR ligation is related to adhesion and metastasis in human colorectal cancer cells and migration in human glioblastoma (via TLR4) and human breast cancer cells (via TLR2)." (PMID 27941651, 2016). "Our findings indicate that PGN-stimulated TLR2 activation in highly metastatic breast cancer MDA-MB-231 cells induced extensive molecular activations involving three important transcriptional factor activities which are essential for control of cancer cell malignant properties." (PMID 20520770, 2010). "We therefore investigated whether TLR2 activation in human breast cancer cells leads to NF-κB activity." (PMID 20520770, 2010). "Our study indicated that TLR2 activation by infectious bacterial PGN played an important role in breast cancer cell invasiveness and illustrated a new link between infectious bacteria and the cancer cells, suggesting the importance of antibiotic therapy to treat cancer with bacterial infection." (PMID 20520770, 2010). "Also in breast cancer, TLR2 is overexpressed in CSCs and promotes their self-renewal." (PMID 41488647, 2025). "Similarly, a positive correlation exists between the expression levels of its partners, TLR1 and TLR6, and the development of brain metastases in breast cancer patients, indicating the potential involvement of the TLR2 heterodimers in the metastatic spread of pre-existing tumors." (PMID 38203626, 2023). "Therefore, TLR2 silencing with specific siRNA significantly impairs tumor growth and prevents the development of lung metastasis in preclinical mouse models of Her2+ breast cancer." (PMID 33321934, 2020). "Therefore, we initially detected TLR2 expression levels of selected breast cancer cell lines." (PMID 20520770, 2010). "To investigate the antitumor immunity induced by the novel Toll-like receptor 2 (TLR2) agonist SUP3 with better stability, we established murine melanoma, colon cancer and breast cancer tumor models." (PMID 41291775, 2025). "Activation of the TLR2/MyD88/NF-κB pathway elevates the autocrine secretion of VEGF and MMP9 in MDA-MB-231 cells, recognized as pivotal factors for breast cancer cell invasion and adhesion." (PMID 38347830, 2024). "Within breast cancer stem cells, the HMGB1/TLR2/MyD88 axis governs NF-κB activation, IL-6 and TGF-β production, and the activation of STAT3 and Smad3." (PMID 38347830, 2024). "Additionally, activation of the TLR2/MyD88 signaling pathway could activate NF-κB and Wnt signaling, participate in the pathogenesis of intracranial aneurysms, and induce the proliferation of colorectal cancer or breast cancer cells." (PMID 38785969, 2024). "In particular, the doxorubicin-induced immunogenic cell death releases TLR2-activating DAMPs, such as HMGB1, able to protects breast cancer cells from chemotherapy and promotes metastasis formation." (PMID 37822929, 2023). "TLR2 activation in CD4+ T cells, triggered by HSP90 on autophagosomes released by breast cancer cells, initiates an autocrine IL-6 cascade." (PMID 38203626, 2023). "In breast cancer, the extracellular HSP90 co-chaperone Morgana acts as another significant activator of TLR2, whereas versican has been identified as the DAMP involved in TLR2-mediated tumor promotion in glioma and lung cancer." (PMID 38203626, 2023).